PAX3 (paired box 3)
Diseases named in the same sentence as PAX3 in open-access papers (continued):
Sharing a sentence is not in itself a finding about the gene and the disease.
rhabdomyosarcoma (continued). "Furthermore, ALK is expressed on the cell surface of rhabdomyosarcomas harboring a PAX3 or PAX7::FOXO1 fusion (fusion-positive rhabdomyosarcoma), the most common soft tissue sarcoma of childhood and adolescence." (PMID 40813394, 2025). "However, these miRNAs are incapable of reducing the expression of the oncogenic fusion protein PAX3::FOXO1 in alveolar rhabdomyosarcoma, as the fusion protein lacks the 3′UTR that would normally be the target for these miRNAs." (PMID 38473380, 2024). "CDKN2A/B), amplifications (e.g. JUN in liposarcoma), fusion partners (e.g. PAX3/7::FOXO1 in rhabdomyosarcoma), breakpoint positions in fusions (e.g. NAB2::STAT6 in SFT) and the extent of segmental (i.e. sub-chromosomal arm) copy number changes (e.g. synovial sarcoma)." (PMID 38997407, 2024). "Alveolar rhabdomyosarcomas (ARMS) are typically driven by chimeric PAX3/PAX7-FOXO1 fusion genes." (PMID 38183459, 2024). "Interestingly, it has been shown that in rhabdomyosarcomas which express the PAX3::FOXO1 fusion protein, Ser205 remains phosphorylated even as myogenic differentiation is triggered." (PMID 38473380, 2024). "Therefore, rhabdomyosarcoma occurs when PAX3 fuses with FOXO1, altering the structure of chromosome 2." (PMID 38540335, 2024). "In addition to myod, previous studies in myoblast and rhabdomyosarcoma cells have shown that pax3 also is involved in supressing apoptosis and regulation of tumour suppressor genes." (PMID 36229514, 2022). "Single-cell PAX3:FOXO1 expression in rhabdomyosarcoma is variable." (PMID 34187933, 2021). "Finally, more comprehensive and detailed studies are needed in order to dissect the global effect of Pax3/7-FKHR fusions on the pathophysiology of Rhabdomyosarcomas." (PMID 33193700, 2020). "In addition to its implication in Rhabdomyosarcoma, misregulation of Pax3 is also related with limb malformations." (PMID 33193700, 2020). "Serine to aspartate conversions at these sites render the transcriptional activity of PAX3/FOX1A fusion proteins insensitive to the inhibitory actions of the kinase inhibitor PKC412, which inhibits growth of alveolar rhabdomyosarcomas carrying a Pax3/Fox1A translocation." (PMID 27906130, 2016). "Likewise, the PAX3-FKHR fusion protein characteristic of alveolar rhabdomyosarcoma was shown to transactivate the IGF1R promoter in sarcoma-derived cell lines." (PMID 27285981, 2016). "In our studies using a conditional genetic mouse model of alveolar rhabdomyosarcoma in conjunction with human tumor cell lines, we have uncovered that the expression level of a translocation-mediated fusion gene, Pax3:Foxo1a, is dynamic and varies during the cell cycle." (PMID 24453992, 2014). "Likewise, knock-down of PAX3 translocation fusion gene PAX3-forkhead (PAX3-FKHR) in alveolar rhabdomyosarcoma (ARMS) cells decreases tumour cell proliferation 17–18." (PMID 24188742, 2014). "BCL2L1 is directly transcriptionally regulated by PAX3, and in rhabdomyosarcoma treatment with PAX3 or BCL2L1 antisense oligonucleotides, individually or in combination, decreases cell viability to a similar extent, suggesting that they lie in the same antiapoptotic pathway." (PMID 20421967, 2010). "In each case, FOXO fusion proteins result from translocations generating chimeric transcripts encoding the N-terminal region of the fusion partner (MLL for the leukemias, and either PAX3 or PAX7 for the rhabdomyosarcomas), and the C-terminal portion of the FOXO component." (PMID 17442120, 2007). "Deregulated expression of oncogenes such as MYC and PAX3-FKHR often occurs in rhabdomyosarcomas." (PMID 17081294, 2006).
rhabdomyosarcoma (continued). "With the difficulties in morphological diagnosis of alveolar rhabdomyosarcoma on increasingly used small needle biopsy specimens, these data suggest that molecular analysis for PAX3-FKHR will be a clinically useful tool in treatment stratification in the future." (PMID 11556833, 2001). "We have determined the presence of the PAX3/7-FKHR fusion genes in 91 primary rhabdomyosarcoma tumours using a combination of classical cytogenetics, FISH and RT-PCR, with a view to determining the clinical characteristics of tumours with and without the characteristic translocations." (PMID 11556833, 2001). "Similarly, in data from the NCBI, we found that the IFFO2 expression level in rhabdomyosarcoma patients with PAX3 and FOXO1 gene fusion, which is considered a predictor of adverse results in children with rhabdomyosarcoma, was lower than those in patients without PAX3 and FOXO1 gene fusion." (PMID 41359381, 2025). "In rhabdomyosarcoma, PAX3 may contribute to apoptotic resistance by reducing PTEN expression." (PMID 38473380, 2024). "Thus, upregulated expression of PAX3 might explain the increased stemness of LTB24 rhabdomyosarcoma cells in our study." (PMID 31941033, 2020). "However, entity-defining fusion oncogenes acting as the main oncogenic driver mutations are frequently found in pediatric bone and soft-tissue sarcomas such as Ewing sarcoma (EWSR1-FLI1), alveolar rhabdomyosarcoma (PAX3/7-FOXO1), and synovial sarcoma (SS18-SSX1/2/4)." (PMID 31970591, 2019). "Therefore, based on these functional backgrounds, silencing of co-activator SS18/SSX picked up small amounts of regulated proteins compared to Ewing sarcoma and alveolar rhabdomyosarcoma having either EWS/FLI1 or PAX3/FOXO1 which act as transcriptional factors." (PMID 30680066, 2018). "Therefore, the PAX3-FOXO1A fusion might hamper the regulation of PAX3 by miRNAs in alveolar rhabdomyosarcoma." (PMID 28895916, 2017). "It will be interesting to determine whether this loop and the signaling bypass created by BRAF-dependent PAX3 phosphorylation is also operative in other tissues and in cancer cells such as rhabdomyosarcoma and melanoma cells, which would offer new refined therapeutic approaches." (PMID 27906130, 2016). "Alveolar rhabdomyosarcoma (RMS), an aggressive pediatric soft tissue cancer, is driven by the oncogenic fusion transcription factor PAX3::FOXO1 (P3F) or PAX7::FOXO1." (PMID 41473312, 2025). "In the future, we plan to use these knockout zebrafish to understand the genetic cooperation between FGFR4 and PAX3::FOXO1, the predominant driver of fusion-positive rhabdomyosarcoma." (PMID 39576839, 2024). "In alveolar rhabdomyosarcoma (ARMS), a chromosomal translocation fusing FOXO1 to either PAX3 or PAX7 is present in about 80% of cases." (PMID 38473380, 2024). "In vitro, AONs targeting PAX3 have been shown to inhibit PAX3::FOXO1 expression and trigger apoptosis in a fusion-positive rhabdomyosarcoma cell line." (PMID 38473380, 2024). "The tumor-specific chromosomal translocation product, PAX3::FOXO1, is an aberrant fusion protein that plays a key role for oncogenesis in the alveolar subtype of rhabdomyosarcoma (RMS)." (PMID 37732905, 2023). "Illustrative examples include Ewing sarcoma (EWS), defined by fusions of the EWSR1 gene with one of the ETS transcription factor genes and fusion-positive rhabdomyosarcoma (RMS), expressing PAX3- or PAX7-FOXO1 (PAX3/7-FOXO1) fusion transcripts." (PMID 35347250, 2022). "Rhabdomyosarcoma (RMS) is the most common soft tissue sarcoma of childhood and adolescence that includes FP-RMS, harboring the fusion oncoprotein PAX3/7-FOXO1 and FN-RMS, often mutant in the RAS pathway." (PMID 36362070, 2022).
rhabdomyosarcoma (continued). "PAX3-FOXO1 or PAX3-FKHR, a specific fusion gene that resulted from chromosomal translocation, is an important factor in the occurrence and development of rhabdomyosarcoma." (PMID 34760693, 2021). "The PAX3-FOXO1 fusion protein contains the PAX3 DNA binding domains and the FOXO1 transactivation domain contributing to the majority of rhabdomyosarcoma cases via impairment of myogenic differentiation." (PMID 34595600, 2021). "This is the case of chromosomal translocations fusing the genes PAX3 and FOXO1 in alveolar rhabdomyosarcoma, which result in the fusion of both RLs and the activation of transcription from PAX3 promoter by enhancers from the FOXO1 RL." (PMID 34295901, 2021). "Our data reveal a hijacked enhancer network that disrupts the stepwise CR TF logic of normal skeletal muscle development (PAX3 to MYOD to MYOG), replacing it with an “infinite loop” enhancer logic that locks rhabdomyosarcoma in an undifferentiated stage." (PMID 32416589, 2020). "This approach enabled us to identify several novel and promising rhabdomyosarcoma CSC-specific targets, e.g., ALDH6A1, SOX4, PAX3, CDH15, downregulated MIR145, or phosphorylated RYK, which warrant validation in subsequent mechanistic studies." (PMID 31941033, 2020). "In tumors with small round cell morphology, amongst nine cases of rhabdomyosarcoma, in eight, RT-PCR for PAX3/7-FOXO1 fusion transcripts was performed and was positive in one case, diagnosed as alveolar rhabdomyosarcoma." (PMID 33061792, 2020). "When PAX3:FKHR expression was targeted by the Myf6 promoter in terminally differentiating skeletal muscle, mice developed alveaolar rhabdomyosarcoma with a very low penetrance (< 1%)." (PMID 27191748, 2017). "Translocations involving PAX3 (or the closely related PAX7) and FOXO1 are only found in rhabdomyosarcomas." (PMID 28615069, 2017). "Similar to the role of EWS-FLI1 in ES, both Pax3:Fkhr and SYT-SSX have been shown to play critical roles in the malignant phenotypes of rhabdomyosarcoma and synovial sarcoma cell lines, respectively." (PMID 27191748, 2017). "The PAX3-FKHR fusion gene results from a translocation between chromosomes 2 and 13 in rhabdomyosarcomas." (PMID 27649156, 2016). "PAX3-FKHR expression enhances the proliferation rate and invasiveness of rhabdomyosarcoma tumors, and enhances expression of the anti-apoptotic protein BCL-XL." (PMID 17081294, 2006). "PAX3 and PAX7 chromosomal translocations define childhood rhabdomyosarcomas, raising the possibility that PAX2 gene rearrangements or deletions might analogously underpin PAX2 expression loss in EC." (PMID 40829174, 2025). "PAX3::NCOA1 and PAX3::NCOA2 fusions are found in rhabdomyosarcoma." (PMID 40599857, 2025). "Multiple alternatively spliced isoforms may also be present at the same time, as is the case for PAX3 and PAX7 in the developing embryo and in rhabdomyosarcoma tumors." (PMID 38473380, 2024). "We validated Pax3-Foxo1 expression in three ACP tumors, none of which expressed the myogenic regulatory transcription factors Myod1 or Myog that are diagnostic for rhabdomyosarcoma." (PMID 37968277, 2023). "Rhabdomyosarcomas (RMS) are pediatric mesenchymal-derived malignancies encompassing PAX3/7-FOXO1 Fusion Positive (FP)-RMS, and Fusion Negative (FN)-RMS with frequent RAS pathway mutations." (PMID 38102140, 2023). "Progression of rhabdomyosarcoma tumours was also delayed in the pax3a/pax3b double mutant zebrafish indicating that Pax3 transcription factors have an unappreciated role in mediating malignancy in fusion negative rhabdomyosarcoma." (PMID 36229514, 2022). "In particular, lowmiR-206 expression correlated with poor overall survival in metastatic embryonal rhabdomyosarcoma and alveolar rhabdomyosarcoma cases without PAX3/7–FOXO1 fusion genes." (PMID 36016604, 2022).
rhabdomyosarcoma (continued). "Alveolar (fusion-positive) rhabdomyosarcoma (FP-RMS), an aggressive skeletal muscle cancer of childhood, often possesses chromosomal translocations, involving commonly PAX3 and FOXO1 genes, rarely PAX7-FOXO1, and in exceptional cases PAX3-INO80D and PAX3-NCOA1 fusions." (PMID 32416589, 2020). "For example, the MYB–NFIB fusion in adenoid cystic carcinoma is regulated by IGF1R through an autocrine loop, and IGF1R is a downstream target of the EWSR1–WT1 and PAX3–FKHR fusions in desmoplastic small round cell tumors and alveolar rhabdomyosarcoma, respectively." (PMID 31426421, 2019). "For example, module 3 contained 139/331 genes upregulated in alveolar compared to embryonic rhabdomyosarcoma, 27/48 genes that were downregulated when FOXO1-PAX3 was altered with RNA interference, and 22/64 genes previously associated with cell line differences related to PAX3 and PAX7 fusions." (PMID 31480361, 2019). "By miRNA profiling, we were able to discriminate the different subtypes of rhabdomyosarcoma: Pax3+ or Pax7+ or fusion negative, classically difficult to diagnose by histological analysis." (PMID 21437224, 2011). "Alveolar rhabdomyosarcoma was ruled out by negative myogenin and myoD1 and by absence of PAX3/PAX7-FKHR translocations by FISH." (PMID 20598147, 2010). "For instance, the diagnosis of alveolar rhabdomyosarcoma (ARMS) is typically based on histopathological features, IHC results (most importantly desmin, MyoD1, and myogenin), and molecular results (RT-PCR for PAX3/PAX7–FOXO1 or FISH for PAX3/FOXO1 rearrangement)." (PMID 37621777, 2023). "Here, we analyse the role of Pax3 in a fusion negative context, by linking alterations in gene expression in pax3a/pax3b double mutant zebrafish with tumour progression in kRAS-induced rhabdomyosarcoma tumours." (PMID 36229514, 2022). "However, bioinformatics analysis exhibited that CCNB1 was significant up‐regulated in Rhabdomyosarcoma patient, which was not consistent with the finding in Neuro‐2a cells overexpressing Pax3." (PMID 33336498, 2021). "Indeed, PAX7 appears to be essential for the rhabdomyosarcoma cell line RD, but not PAX3 (bottom row)." (PMID 30683138, 2019). "However, most of these genes from differentially co-expression fusion positive modules reported no known responses to PAX3 or PAX7 in rhabdomyosarcoma or other cancers." (PMID 31480361, 2019). "However, its role as a cooperating gene in PAX3/7-FOXO1 fusion-positive rhabdomyosarcoma has never been described." (PMID 29869612, 2018). "They repress the protein expression of PAX3 in embryonal, but not alveolar, rhabdomyosarcoma." (PMID 28895916, 2017). "In this study, we hypothesized that screening a small-molecule library might identify already existing drugs that are able to modulate the transcriptional activity of PAX3/FOXO1, the fusion protein specifically found in the pediatric tumor alveolar rhabdomyosarcoma (aRMS)." (PMID 23372815, 2013). "From a molecular biological viewpoint, it distinguishes two major groups based on the PAX3/7-FOXO1 fusion gene status, namely, fusion-positive rhabdomyosarcoma (FPRMS), and fusion-negative rhabdomyosarcoma (FNRMS)." (PMID 35128576, 2022). "Rhabdomyosarcoma (RMS) is an aggressive pediatric malignancy of the muscle, that includes Fusion Positive (FP)-RMS harboring PAX3/7-FOXO1 and Fusion Negative (FN)-RMS commonly with RAS pathway mutations." (PMID 33420019, 2021). "Rhabdomyosarcoma is subclassified by the presence or absence of a recurrent chromosome translocation that fuses the FOXO1 and PAX3 or PAX7 genes." (PMID 31480361, 2019).
melanoma (92 papers, 2007 to 2026). A malignant, usually aggressive tumor composed of atypical, neoplastic melanocytes. "In SK-MEL-5 melanoma cells, PAX3 is bound to DNA elements associated with genes involved with transcription, RNA modification, cell growth, and neuronal growth, function, and signaling." (PMID 40428399, 2025). "PAX3, a key transcriptional regulator involved in melanocyte development, has also been implicated in melanoma pathogenesis." (PMID 40216818, 2025). "PAX3 has been associated with the survival of melanoma cells and is considered essential for the viability of melanoma cell lines." (PMID 38928435, 2024). "The co-expression of PAX3 with melanocyte markers and its association with increased proliferation suggest that PAX3 may contribute significantly to melanoma development." (PMID 40216818, 2025). "Both, c-MET as well as PAX3, have previously been implicated in melanoma cell survival." (PMID 28978033, 2017). "We next investigated whether expression of PAX3 is associated with loss of growth control in melanoma, which is a role that MITF has been implicated, as might be expected if PAX3 and MITF were to function in the same or similar pathways." (PMID 24062982, 2013). "Importantly, immunohistochemical analyses of primary and metastatic melanoma patient samples in a tissue microarray, showed that molecular markers of collagen levels were associated with the transcriptomic signature for melanoma cell phenotypic dedifferentiation via the YAP/PAX3/MITF axis." (PMID 36119516, 2022). "On the other hand, PAX3 expression is maintained in melanoma, in early lesions, primary tumors and metastasis." (PMID 40428399, 2025). "This increased PAX3 expression was observed in both the epithelial and stromal components of the melanoma lesions." (PMID 40216818, 2025). "To elucidate this, we performed immunohistochemical analysis of conjunctival melanoma tissues as well as in limbal melanoma tissues, which confirmed strong PAX3 expression in melanoma cells compared to melanocytes in healthy counterpart tissues." (PMID 40216818, 2025). "This increased PAX3 expression was noted in both the epithelial and stromal components of the melanoma lesions." (PMID 40216818, 2025). "SOX family members are common PAX protein co-factors; in melanocytes and melanoma, PAX3 interacts with SOX10 and drives a number of downstream genes, such as MITF, MET, and RET." (PMID 40428399, 2025). "The co-expression of PAX3 with Melan-A, a specific marker for melanocytes, confirms that the PAX3+ cells in the melanoma tissues are of melanocytic origin." (PMID 40216818, 2025). "Clearly, the PAX3-dependent influence on melanoma maintenance and progression is much wider than the few known downstream genes already identified." (PMID 40428399, 2025). "PAX3 is known to drive expression of genes involved in both an invasive and proliferative phenotype in melanoma, and TFAP2A can work as a rheostat switch between phenotypic groups." (PMID 40428399, 2025). "YAP/TAZ-induced differentiation of melanoma cells occurs through a transcriptional interaction with PAX3 (Paired box 3), which activates MITF gene expression in these cells." (PMID 40399946, 2025). "Background/Objectives: PAX3 is a transcription factor that drives melanoma progression by promoting cell growth, migration, and survival, while inhibiting cellular terminal differentiation." (PMID 40428399, 2025). "Our findings suggest that the MC extract suppresses tumor survival genes by regulating PAX3, thereby ameliorating melanoma proliferation and invasion." (PMID 39684511, 2024). "PAX3 and PAX7 are expressed in melanomas and sarcomas, and have been associated with tumor-promoting activity." (PMID 38473380, 2024). "Previous research suggests that the MC extract suppresses melanoma proliferation and invasion by decreasing PAX3 expression and regulating PTEN/PI3K/Akt signaling." (PMID 39684511, 2024).